PPARA (peroxisome proliferator activated receptor alpha)
Diseases named in the same sentence as PPARA in open-access papers (continued):
Sharing a sentence is not in itself a finding about the gene and the disease.
Stroke (continued). "In this study, we modeled ischemic stroke in wild-type (WT) and PPARα genetic knockout (KO) mice and utilized the RNA-sequencing of ipsilesional hemisphere brain tissue harvested 48 hours (h) post-stroke to characterize genes and transcriptional pathways associated with PPARα." (PMID 40362325, 2025). "Thus, in addition to limiting neuroinflammation, PPARα activation likely protects the brain following stroke by also modulating genes involved in apoptosis, EMT, and the disassembly of cellular components." (PMID 40362325, 2025). "Interestingly, we observed the transcriptional enrichment of several of these pathways in the brains of our PPARα KO mice during the subacute stroke phase." (PMID 40362325, 2025). "We assessed the effects of PPARα genetic deletion on infarct volume in mouse stroke brains." (PMID 40362325, 2025). "Some preclinical studies suggest that treatment with PPARα agonists benefits stroke outcome by eliciting anti-inflammatory effects in the CNS and the periphery, while other studies report that PPARα activation reduces endothelial dysfunction and blood–brain barrier (BBB) breakdown after stroke." (PMID 40362325, 2025). "A complementary positive approach using gain-of-function studies with constitutive PPARα signaling in different types of brain cells will help to validate our findings and identify additional PPARα-regulated pathways that may benefit stroke outcomes." (PMID 40362325, 2025). "Additionally, our study showed that PPARα signaling is involved in the inhibition of glial scarring after stroke." (PMID 37111378, 2023). "However, how PPARα participates in this M2-M1 phenotype switch in chronic inflammation after a stroke still needs further study." (PMID 37111378, 2023). "Dual PPARα/γ agonist improves stroke outcome after transient cerebral ischemia in mice." (PMID 34168538, 2021). "Our previous study in mice showed that resveratrol-mediated protection of the brain against stroke requires activation of PPARα; however, the molecular mechanisms involved in this process remain unknown." (PMID 25798826, 2015). "Future studies using PPARα transgenic mice to model ischemic stroke may consider monitoring physiological and biochemical variables, such as lipid profiles, glucose levels, and liver function, to better assess how the metabolic consequences of PPARα modulation may affect stroke pathophysiology." (PMID 40362325, 2025). "Therefore, OEA might be a promising therapeutic drug for stroke and targeting PPARα-mediated M2 microglia may represent a new strategy to treat ischemic stroke." (PMID 37111378, 2023). "Using qRT‐PCR assays, we detected elevated mRNA expression of FA transporter CD36 and key mediators in FA β‐oxidation, including CPT1α, PPARα and ACOX1, confirming a hepatic shift towards enhanced FAO following stroke." (PMID 38666466, 2024). "Overall, our results suggest that PPARα signaling may blunt signaling pathways that promote inflammation and BBB breakdown in the subacute stroke phase to reduce the infarct volume." (PMID 40362325, 2025). "Next, based on knowledge that fenofibrate and Brassica Oleracea (BO) stimulate UCP2 expression through PPARα activation, we monitored stroke occurrence in SHRSP receiving JD plus fenofibrate versus vehicle, JD plus BO juice versus BO juice plus PPARα inhibitor." (PMID 28640254, 2017). "We found one study where a PPARα agonist treatment before a stroke was neuroprotective in male mice but not females, suggesting that perturbation of PPARα might be sex-dependent." (PMID 38167211, 2024). "However, whether PPARα participates in the microglia M1-M2 phenotype switch in inflammation after stroke has not yet been explored." (PMID 37111378, 2023).
hypertrophic cardiomyopathy (30 papers, 2012 to 2025). A condition in which the myocardium is hypertrophied without an obvious cause. "In this study, we reveal that the bioactive ingredients of C. reticulata potentially target PPARα and PPARβ to alleviate hypertrophic cardiomyopathy." (PMID 40832599, 2025). "Specifically, regulation of genes involved in Biocarta PPARα pathway, GO response to oxidative stress, and KEGG hypertrophic cardiomyopathy pathway were assessed in LV tissue isolated from WT, PPARα−/− and Nox2−/− mice subjected to TAC." (PMID 32575797, 2020). "Interestingly, PPARα was one of the overlapping genes, which was consistent with the potential targets of C. reticulata related to hypertrophic cardiomyopathy." (PMID 40832599, 2025). "Our results showed that nobiletin, a key active ingredient of C. reticulata, improves myocardial lipid metabolism by directly targeting peroxisome proliferator-activated receptor alpha (PPARα) and inhibiting the phenylephrine (PE)-induced hypertrophic cardiomyopathy responses in vitro." (PMID 40832599, 2025). "In this study, our PPI network results revealed that PPARα, PPARγ, and CREB1 were the potential targets of C. reticulata with higher relevance for combating hypertrophic cardiomyopathy." (PMID 40832599, 2025). "WT animals displayed significant alterations (FDR < 0.25) in GO response to oxidative stress, with no alterations to Biocarta PPARα pathway or KEGG hypertrophic cardiomyopathy pathway." (PMID 32575797, 2020). "Notably, all three pathways remained unaltered in LV tissue from Nox2−/− mice subjected to TAC, whilst PPARα−/− mice showed significant alterations to both GO response to oxidative stress and KEGG hypertrophic cardiomyopathy pathway, consistent with the observed worsened LVH phenotype." (PMID 32575797, 2020).
myocardial ischemia (30 papers, 2010 to 2026). A disorder of cardiac function caused by insufficient blood flow to the muscle tissue of the heart. "In summary, the deregulation of FATP, CPTI and PPARα could be the cause of fatty acids metabolism disorders in myocardial ischemia model." (PMID 25885422, 2015). "It was shown that activated PPARα exerted a protective effect by inhibiting endoplasmic reticulum stress induced by myocardial ischemia/reperfusion injury." (PMID 38641695, 2024). "Among eight miRNAs, miRNA-292-5p, which participates in myocardial ischemia–reperfusion injury by activating the peroxisome proliferator-activated receptor-α/-γ (PPARα/PPARγ)-dependent signaling pathway, has been studied since 2018." (PMID 36266609, 2022). "Activation of PPARα results in the protection against ischemia-reperfusion injury induced by myocardial ischemia." (PMID 30911353, 2019). "The activation of PPARα protects myocardial cells by increased expression and activation of superoxide dismutase (SOD1, SOD2) and catalase and suppresses the generation of ROS in myocardial ischemia." (PMID 30911353, 2019). "Despite the fact that PPARα regulate UCPs levels, the influence of PPARα on UCPs and resultant ROS generation during myocardial ischemia-reperfusion has not been elucidated heretofore." (PMID 26770648, 2016). "Furthermore, the transcription factors PPARα and RXR which could promote β oxidation of fatty acids, were also decreased in the myocardial ischemia model." (PMID 25885422, 2015). "Moreover, activation of peroxisome proliferator-activated receptor alpha (PPAR-α) reduces oxidative stress and improves ventricular ultrastructure and hemodynamics in myocardial ischemia without flow." (PMID 40298815, 2025).
psoriasis (29 papers, 2010 to 2026). An autoimmune condition characterized by red, well-delineated plaques with silvery scales that are usually on the extensor surfaces and scalp. "Subsequent molecular biology experiments demonstrated that brusatol ameliorates psoriasis-associated dyslipidemia by modulating the AMPK-mediated SREBP-1c/FASN and PPARα/CPT1A signaling pathways." (PMID 41508030, 2026). "Collectively, these results establish FADS2 as an essential downstream effector for PPARα‐mediated immune modulation in psoriasis." (PMID 40878384, 2025). "Consistent findings were observed in IMQ‐induced murine psoriasis, where both PPARα and FADS2 expression were reduced in lesional epidermis compared to controls." (PMID 40878384, 2025). "Depending on the experimental set‐up, PPARα expression is decreased or remains unchanged in atopic dermatitis (AD) and psoriasis, respectively." (PMID 33683743, 2021). "T cell activation in psoriasis patients also resulted in a significant enrichment of genes involved in PPARα-mediated activation of gene expression (FDR = 0.0043) and cholesterol biosynthesis (FDR = 0.0063)." (PMID 24267790, 2013). "An increased expression of PPARβ/δ and a decreased expression of PPARα and PPARγ were observed in the lesional skin of patients with psoriasis and atopic dermatitis." (PMID 20706605, 2010). "Both data sets confirm highly significant upregulation of PPARβ/δ in psoriatic skin whereas both PPARα and PPARγ are downregulated, consistent with the notion that PPARβ/δ acts antagonistically to PPARγ in psoriasis, as previously proposed." (PMID 20300524, 2010). "An mRNA profiling analysis of skin biopsies from patients with atopic dermatitis and psoriasis revealed that PPARα and PPARγ are downregulated in the itchy skin regions of psoriasis patients, while PPARα remains unchanged in patients with atopic dermatitis and PPARγ increases by 24%." (PMID 36552866, 2022). "Additionally, PPARα plays a role in regulating skin inflammation in diseases such as AD and psoriasis by modulating cytokine expression, T cell proliferation, as well as the maturation and migration of Langerhans cells." (PMID 33424605, 2020). "In lesional skin of patients with psoriasis and atopic dermatitis the expression of PPARD was also increased while the expression of PPARA and PPARG was decreased." (PMID 21573029, 2011). "PPARα transcriptionally activates FADS2, and its activation alleviates inflammation in a FADS2‐dependent manner, highlighting a therapeutic axis to restore immune homeostasis in psoriasis." (PMID 40878384, 2025). "To assess whether FADS2 is required for PPARα‐mediated suppression of psoriatic inflammation in vivo, we knocked down Fads2 using siRNA and administered WY14643 in IMQ‐induced psoriasis‐like skin lesions." (PMID 40878384, 2025).
cardiomyopathy (28 papers, 2012 to 2025). A disease of the heart muscle or myocardium proper. "The downregulation of PDK4 may be accounted for by the suppression of the expression of cardiac PPARα that has been reported in aging-associated cardiomyopathy." (PMID 33995129, 2021). "A study has shown that GSK-3α promotes fatty acid uptake in cardiomyocytes, eventually leading to lipotoxic cardiomyopathy through phosphorylation of PPARα." (PMID 40836599, 2025). "Overexpression of PPARα in mice leads to severe cardiomyopathy, while inhibition of PPARα prevents the progression of DCM." (PMID 38715043, 2024). "The authors discussed that mitochondrial dysfunction due to increased cardiac FA uptake provokes deleterious lipotoxic cardiomyopathy similar to mice with cardiac-specific overexpression of PPARα." (PMID 37150323, 2023). "This notion is supported by the experimental data that over-expression of PPARα resulted in the development of severe cardiomyopathy in mice, whereas inhibition of PPARα prevented the development of DCM." (PMID 33397369, 2021). "Since disturbances in PPARα and PPARδ regulated FAO has been implicated in cardiomyopathy, we inferred that Med1 deletion in cardiomyocytes perturbs myocardial FAO and energy metabolism in csMed1-/- hearts." (PMID 27548259, 2016). "Combined cardiac-specific loss of both PHD2 and PHD3 results in increased expression of phosphoglycerate kinase, decreased expression of PPARα, myocyte accumulation of lipid, and severe cardiomyopathy." (PMID 27422990, 2016). "PPARα stimulation by the drug Bezafibrate has previously been shown to ameliorate the cardiomyopathy symptoms of TAZ knockdown mice, and is currently the subject of a clinical trial, and therefore PPARα activating compounds are of clinical interest in this disease." (PMID 35676289, 2022). "It was noted that cardiac hypertrophy and cardiomyopathy was induced by the overexpression of MG53, which may be associated with PPARα-induced lipid toxicity." (PMID 34183055, 2021). "Activation of the PPARα led to lipogenesis in cardiomyocytes, resulting in cardiomyopathy." (PMID 31604915, 2019). "Moreover, hearts overexpressing PPARα showed signs of cardiomyopathy." (PMID 22672789, 2012). "A plausible mechanism accounting for miR-22-mediated GOF cardiomyopathy came from our observation that vital cardiac genes SIRT1, PGC-1α, and PPARα are co-repressed by miR-22 in the heart." (PMID 24086656, 2013).
type 1 diabetes (28 papers, 2008 to 2026). "Fenofibrate, a peroxisome proliferator-activated receptor alpha agonist, shows some promise in alleviating beta cell stress and preserving beta cell function in preclinical studies of type 1 diabetes." (PMID 39477880, 2025). "The expression of hepatic CYP8B1 is regulated exactly as HSDL2: It is (i) increased upon fasting, (ii) activated by PPARα agonists, (iii) repressed by insulin, and (iv) elevated in type 1 diabetes." (PMID 38820148, 2024). "Previous studies have shown that conditions such as fasting, PPARα stimulation, and type 1 diabetes, which we found to promote HSDL2 expression, often associate with alterations in BA pool composition rather than total BA levels." (PMID 38820148, 2024). "We identified for the first time that PPARα is neuroprotective in retinopathy of type 1 diabetes, and subsequently sought to identify the molecular basis for this effect." (PMID 30716067, 2019). "Here we reveal that activation of PPARα had a robust protective effect on retinal function as shown by Optokinetic tracking in a rat model of type 1 diabetes, and also decreased retinal cell death, as demonstrated by a DNA fragmentation ELISA." (PMID 30716067, 2019). "In this study, we sought to determine if PPARα is also neuroprotective in retinopathy of type 1 diabetes using both functional and biochemical analyses in rats treated with fenofibrate, and in diabetic Pparα-/- mice." (PMID 30716067, 2019). "The overarching goal of these studies was to evaluate neuroprotective effects of PPARα in retinopathy of type 1 diabetes, and assess its molecular mechanisms of action." (PMID 30716067, 2019). "In the present study, we demonstrated for the first time that PPARα is neuroprotective in retinopathy of type 1 diabetes, and is therefore a potential therapeutic for DR in type 1 diabetic patients." (PMID 30716067, 2019). "Together, these findings suggested that long-term treatment with a PPARα agonist protected retinal function in type 1 diabetes, and that short term treatment alleviated retinal apoptosis." (PMID 30716067, 2019). "Moreover, PPARα agonist was described to prevent fibrosis in the heart of type 1 diabetic mice (T1DM) via the FGF21/PPAR/Sirt1 signaling pathway." (PMID 35677107, 2022). "Together, these findings demonstrate a potent antioxidant effect for PPARα in retinopathy of type 1 diabetes, which may be modulated in part through improved mitochondrial dysfunction and subsequent decreases in ROS production." (PMID 30716067, 2019). "We revealed here that PPARα is neuroprotective in retinopathy of type 1 diabetes, and that these effects may be mediated in part through improved mitochondrial efficiency and subsequent decreases in mitochondrial ROS production." (PMID 30716067, 2019). "In a type 1 diabetes model, impaired insulin signaling promoted cardiac oxidative stress by activating FOXO1 and the expression of PPARα in cardiomyocytes." (PMID 40313619, 2025). "Another study on type 1 diabetes indicated that intraocular injection of fenofibrate ameliorates retinal inflammation in OIR rats, and these therapeutic effects on DR are PPARα dependent, suggesting PPARα as a potential target of DR cure." (PMID 36589809, 2022).
Cognitive impairment (27 papers, 2010 to 2026). Abnormal cognition is characterized by deficits in thinking, reasoning, or remembering. "As cell energy metabolism and synaptic activity are closely related, it is still questionable whether a PPARα agonist or antagonist could help for synaptic abnormalities associated with cognitive impairments observed in AD." (PMID 34228639, 2021). "PPARα mediates the improvement of hippocampal synaptic plasticity upon nuclear retinoid X receptor (RXR) activation in a transgenic mouse model with cognitive deficits." (PMID 40040308, 2025). "Reduction in hepatic LRP-1 regulated by PPARα contributes to impaired peripheral Aβ clearance, thereby leading to cerebral Aβ accumulation and cognitive impairment in NAFLD." (PMID 38507874, 2024). "We report that PPARα mediates the improvement of hippocampal synaptic plasticity upon RXR activation in a transgenic mouse model with cognitive deficits." (PMID 30894406, 2019). "Administration of PPARα agonist fenofibrate preserved hippocampal neurogenesis and prevented radiation-induced cognitive impairment; the application of pioglitazone, the PPARγ agonist, significantly recovered cognitive impairment in irradiated rats." (PMID 31450566, 2019). "In view of this, we could argue that the alterations in the gene expression of CB2 and PPARα in the PFC of cisplatin-treated rats may be related to acute neuroinflammatory processes that may have induced cognitive deficits in these animals." (PMID 39458898, 2024). "Similarly, the PPARα agonist FF, as a selective synthetic agonist of PPARα, has been demonstrated to exert significant ameliorating effects on cognitive impairment in animal experiments and clinical patients of AD and PD." (PMID 38023298, 2023). "Although this study strongly supports that targeting PPARα could be an effective strategy to improve synaptic plasticity deficits related to cognitive defects, it presents some limitations." (PMID 30894406, 2019). "Therefore, OEA and others putative PPARα activators are interesting targets to be further investigated to unveil novel therapeutic strategies approaching cognitive impairment and pathologies related to AUD." (PMID 31068789, 2019). "The PPARα agonist FF might be a novel target for therapeutic schemes of cognitive disorders." (PMID 38023298, 2023). "PPARα KO mice exhibit a decrease in startle reflex in the PPI test and an increase in perseverative and repetitive behaviors and cognitive deficits indicative of impaired cognitive flexibility." (PMID 35625650, 2022). "Together, these findings suggested that ICS II attenuates CCH-induced cognitive deficits by inhibiting the amyloidogenic pathway via involvement of BDNF/TrkB/CREB signaling and up-regulation of PPARα and PPARγ in rats." (PMID 30405422, 2018). "Second, we found that NAFLD hindered the hepatic uptake of Aβ via the PPARα/LRP-1 pathway, but studies in hepatocyte-specific LRP-1 or PPARα overexpression animal models challenged with a long-term HFD are required to clarify its role in NAFLD-induced Aβ pathology and cognitive impairment." (PMID 38507874, 2024). "PPARα activation prevents perirhinal cortex-dependent cognitive impairment without a decrease in microglial activation and an increase in immature neurons." (PMID 35955439, 2022). "In addition, neither PPARα nor PPARδ activation improved hippocampal-dependent cognitive impairment in rats, which is not compatible with reduced neuroinflammation and fewer activated microglia in the hippocampus." (PMID 35955439, 2022). "The data clearly demonstrated that ICS II might produce protective effect against BCCAO-induced cognitive impairment by up-regulating the expressions of PPARα and PPARγ, not by retarding the decrease of the expressions of PPARα and PPARγ." (PMID 30405422, 2018).
Cognitive impairment (continued). "With reference to PPARα, although we demonstrated that fenofibrate prevented the detrimental effect of WBI on hippocampal neurogenesis and inhibited microglial activation, we were unable to use the mouse model to test whether it can inhibit radiation-induced cognitive impairment." (PMID 19789638, 2010).